PTPRO (protein tyrosine phosphatase receptor type O)
Diseases named in the same sentence as PTPRO in open-access papers (continued):
Sharing a sentence is not in itself a finding about the gene and the disease.
colon cancer (3 papers, 2013 to 2022). "Our results revealed that loss of PTPRO promotes resistance to EGFR inhibitors in colon cancer cells by maintaining activated SRC and EGFR/MAPK pathway." (PMID 25301722, 2014). "Importantly, hyperactivation of SRC/EGFR signaling triggered by loss of PTPRO leads to high resistance of colon cancer to EGFR inhibitors." (PMID 25301722, 2014). "Here we found that up-regulation of SRC activity by loss of PTPRO dramatically affects activation of EGFR/MAPK pathway, further confirming the contribution of the SRC kinase to colon cancer development and progression." (PMID 25301722, 2014). "qRT-PCR analysis of colon cancer cell lines revealed that the mRNA expression levels of PTPRO were dramatically down-regulated in 10 of 14 colon cancer cell lines." (PMID 25301722, 2014). "Taken together, our results strongly indicate that PTPRO expression affects the sensitivity of colon cancer cells to EGFR inhibitors." (PMID 25301722, 2014). "Gene expression analysis of 688 colon cancer patient reveals decreased PTPRO expression in about 15% of all colon cancers." (PMID 25301722, 2014). "Recent gene expression analysis of 688 primary colon tumors revealed that PTPRO mRNA expression is strongly down-regulated in colon cancer patients with a poor prognosis." (PMID 25301722, 2014). "PTPRO protein levels were also reduced in most of the analyzed colon cancer cell lines, indicating that PTPRO expression is commonly down-regulated in colon cancer cell lines." (PMID 25301722, 2014). "To date, only few data have been published about the contribution of PTPRO in colon cancer." (PMID 25301722, 2014). "To expand this observation, we analyzed PTPRO expression in colon cancer cell lines." (PMID 25301722, 2014). "In contrast, suppression of PTPRO in LIM1215 and HCA46 colon cancer cells led to enhanced phosphorylation of the MAPK kinases." (PMID 25301722, 2014). "We observed similar results when we overexpressed WT-PTPRO in CACO2 colon cancer cell line, which does not express PTPRO." (PMID 25301722, 2014). "Our results strongly imply PTPRO in negative regulation of EGFR signaling, suggesting that PTPRO expression could affect the sensitivity of colon cancer cells to EGFR inhibitors." (PMID 25301722, 2014). "In CC there are no studies describing the implication of PTPRO in drug resistance, but this gene was found to be methylated in colon tumors." (PMID 23865481, 2013).
diabetes (3 papers, 2006 to 2017). "The previously identified UMOD locus showed genome-wide significant association with eGFRcrea among those with diabetes (rs12917707, P value=2.5 × 10−8), and six loci (NFKB1, UNCX, TSPAN9, AP5B1, SIPA1L3 and PTPRO) had nominally significant associations with eGFRcrea among those with diabetes." (PMID 26831199, 2016). "However, PTPRO mRNA, which encodes for GLEPP-1 has been evidenced in the urinary cells of rats with streptomycin-induced diabetes, while human studies are lacking." (PMID 28484521, 2017).
esophageal cancer (3 papers, 2014 to 2025). A primary or metastatic malignant neoplasm involving the esophagus. "We have demonstrated that PTPRO inhibits oesophageal cancer lymph node metastasis by dephosphorylating MET7." (PMID 40016288, 2025). "Hypermethylation of PTPRO occurs frequently in esophageal carcinoma and may be a potential biomarker of the disease." (PMID 24919593, 2014).
lung adenocarcinoma (3 papers, 2021 to 2024). A carcinoma that arises from the lung and is characterized by the presence of malignant glandular epithelial cells. "Meanwhile, IHC analysis was conducted to assess the protein expressions of p-JAK2, p-STAT3, Bcl-2, Snail, and PTPRO in tissue sections obtained from ten cases of clinical lung adenocarcinoma specimens." (PMID 38182570, 2024). "However, the comprehensive functions and mechanisms of PTPRO in lung adenocarcinoma (LUAD) progression are poorly understood." (PMID 38182570, 2024). "However, the function and the underlying mechanisms of PTPRO in regulating of lung adenocarcinoma (LUAD) are not well understood." (PMID 38182570, 2024). "Examination of TCGA datasets demonstrated that CT-RERG transcription is significantly correlated with PTPRO and RERG promoter hypermethylation in lung adenocarcinoma tissues." (PMID 34462486, 2021).
lymphoma (3 papers, 2017 to 2021). A malignant (clonal) proliferation of B- lymphocytes or T- lymphocytes which involves the lymph nodes, bone marrow and/or extranodal sites. "According to the results, PTPRO was upregulated in breast, leukemia, lymphoma, colorectal, pancreatic cancers, and melanoma, relative to the matched normal tissues." (PMID 35003364, 2021).
renal carcinoma (3 papers, 2021 to 2023). A carcinoma arising from the epithelium of the renal parenchyma or the renal pelvis. "A previous study demonstrated that PTPRO can improve TIM in renal cancer, and given the findings we obtained, PTPRO has a similar effect in LUAD." (PMID 36816740, 2023). "PTPRO and FGF1 were already established prognostic biomarkers of renal cancers." (PMID 34557161, 2021).
colon adenocarcinoma (2 papers, 2021 to 2024). "Significant upregulation of PTPRO was observed in colon adenocarcinoma (COAD), pancreatic adenocarcinoma (PAAD), rectum adenocarcinoma (READ), and acute myeloid leukemia (LAML), in comparison to matched normal tissues." (PMID 35003364, 2021). "For example, PTPRO was upregulated in cholangiocarcinoma (CHOL) and colon adenocarcinoma (COAD), while downregulated in bladder cancer (BLCA) and kidney chromophobe (KICH)." (PMID 38182570, 2024).
gestational diabetes mellitus (2 papers, 2021). "The current study has firstly suggested that PTPRO is upregulated in placenta-derived macrophages from gestational diabetes mellitus patients." (PMID 34007244, 2021). "Reversely, increased expression of PTPRO was found in placenta-derived macrophages from patients with gestational diabetes mellitus." (PMID 34007244, 2021). "In summary, the present study has identified a miR-6869-5p signature involvement in gestational diabetes mellitus, which may contribute to maintain the balance of placental immune microenvironment by targeting PTPRO and inducing macrophages polarization towards M2." (PMID 34007244, 2021). "Besides, PTPRO has been proved to be highly expressed in placenta-derived macrophages from patients with gestational diabetes mellitus and could participate in maintaining placental microenvironment balance." (PMID 34719307, 2021).
leukemia (2 papers, 2021 to 2025). A malignant (clonal) hematologic disorder, involving hematopoietic stem cells and characterized by the presence of primitive or atypical myeloid or lymphoid cells in the bone marrow and the blood. "A few studies utilized human leukemia cell lines transfected with miR-657 and miR-6869-5p, identifying IL-37 and PTPRO as target genes involved in the anti-inflammatory response." (PMID 40559391, 2025).
liver cancer (2 papers, 2021 to 2022). An epithelial or non-epithelial malignant neoplasm that arises from the liver. "ERα is demonstrated to up-regulate the expression of Protein Tyrosine phosphatase receptor Type O (PTPRO), which plays an inhibitory role in liver cancer." (PMID 36060947, 2022).
liver fibrosis (2 papers, 2016 to 2021). "PTPRO causes ulcerative colitis through TLR4/NF-KB signaling pathway and plays a role in liver fibrosis by affecting PDGF signaling in HSC activation." (PMID 33462260, 2021). "PTPRO knockout mice [PTPRO(-/-)] have attenuated liver injury, release of inflammatory factors, tissue remodeling, and liver fibrosis in fibrogenesis induced by BDL or carbon tetrachloride (CCl4) administration." (PMID 26909046, 2016).
lung squamous cell carcinoma (2 papers, 2022). "PTPRO is down-regulated in injured podocytes and lung squamous cell carcinoma compared with healthy tissues." (PMID 35906634, 2022).
lymph node metastasis (2 papers, 2013 to 2014). "To confirm the significance of this finding, we performed multivariate analysis, treating methylated-PTPRO/HER2-positivity as a factor with tumor size, lymph node metastasis, histological grade and HER2 status for their impact on overall survival." (PMID 24090193, 2013).
nonalcoholic steatohepatitis (2 papers, 2020 to 2022). "The expression of PTPRO truncated isoform (PTPROt) is increased in liver macrophages with the increasing degree of nonalcoholic steatohepatitis." (PMID 35906634, 2022).
acute lymphoblastic leukemia (1 paper, 2017). Leukemia with an acute onset, characterized by the presence of lymphoblasts in the bone marrow and the peripheral blood. "Notably, a recent study found aberrant methylation of several membrane-bound tyrosine phosphatase genes in acute lymphoblastic leukemia including PTPRO, and this was associated with a reduction in phosphorylated Extracellular signal-regulated kinases 1/2 and AKT, among others." (PMID 29371952, 2017).
alcohol addiction (1 paper, 2023). "In addition, it has been reported that PTPRO downregulation can be related to viral infections, sleep deprivation, systemic inflammation, alcohol addiction, corticosterone levels, anxiety, unpredictable chronic mild stress, prenatal stress, and high-fat diet." (PMID 37485875, 2023).
autoimmune thyroid disease (1 paper, 2024). Inflammatory disease of the thyroid gland due to autoimmune responses leading to lymphocytic infiltration of the gland. "The results indicated that PTPRO expression was linked to systemic lupus erythematosus, phagocytosis, autoimmune thyroid disease, NK cell-mediated cytotoxicity, and apoptosis." (PMID 38182570, 2024).
B-cell chronic lymphocytic leukemia (1 paper, 2022). "PTPRO’s impact on B cell proliferation is supported by aberrant expression in B-cell chronic lymphocytic leukemias and by the detection of a shared germline PTPRO variant (rs6175411) in a pair of monozygotic twins with hematological pre-malignancies." (PMID 36755664, 2022).
B-cell lymphoma (1 paper, 2021). "For example, two cohorts (GSE4475 and GSE5122) included 158 B-cell lymphoma samples and 58 AML samples revealed that PTPRO upregulation was related to poorer prognosis (OS HR = 2.02, 95% CI = 1.46 to 2.18, Cox P = 0.00002; OS HR = 1.62, 95% CI=1.12 to 2.34, Cox P = 0.01)." (PMID 35003364, 2021).
chronic obstructive pulmonary disease (1 paper, 2022). A chronic and progressive lung disorder characterized by the loss of elasticity of the bronchial tree and the air sacs, destruction of the air sacs wall, thickening of the bronchial wall, and mucous accumulation in the bronchial tree. "Additionally, in one of the first WGS studies addressing hereditary factors predisposing for chronic obstructive pulmonary disease (COPD) this PTPRO gene variant rs61754411 came out as number one association across the exome (p = 4.0 × 10–5), although genome-wide significance was not reached." (PMID 36755664, 2022).
clear cell renal cell carcinoma (1 paper, 2021). "Together with the finding that PTPRO expression is correlated with the activation of immune response in human clear cell renal cell carcinoma, the potential role of PTPRO in immune regulation has been noticed." (PMID 34650968, 2021).
cognitive disorder (1 paper, 2023). A disease affects cognitive processes. "Since impaired kidney function is closely related to cognitive disorders, we further examined the relevance of kidney PTPRO to cognitive function in DOX-induced CRCI." (PMID 37485875, 2023).
Cognitive impairment (1 paper, 2023). Abnormal cognition is characterized by deficits in thinking, reasoning, or remembering. "We show that hippocampal PTPRO deficiency not only led to CRCI-relevant cognitive impairment in mice, but also conferred therapeutic vulnerability that could be targeted by repurposing BBR." (PMID 37485875, 2023).
Dyskinesia (1 paper, 2022). A movement disorder which consists of effects including diminished voluntary movements and the presence of involuntary movements. "In contrast, serotoninergic neurons, the potential source of graft-induced dyskinesia, and GABAergic neurons were largely absent from the CLSTN2- and PTPRO-sorted grafts." (PMID 35700056, 2022).
emphysema (1 paper, 2021). "It is noteworthy that PTPRO is a new candidate gene for emphysema with severe obstruction." (PMID 33462260, 2021).
endometriosis (1 paper, 2025). The growth of functional endometrial tissue in anatomic sites outside the uterine body. "Wnt protein binding (GOMF) was a significant pathway in our gene set analyses, with five genes overlapping with our biologically-implicated endometriosis gene set: CTHRC1 (mSMR), FZD6 (fibroblast-eSMR), PTPRO (fibroblast-, ovary-, and whole blood-TWAS), RECK (fibroblast-sSMR), and TRABD2A (mSMR)." (PMID 41377979, 2025).
epilepsy (1 paper, 2024). A brain disorder characterized by episodes of abnormally increased neuronal discharge resulting in transient episodes of sensory or motor neurological dysfunction, or psychic dysfunction. "Our eQTL analysis revealed that several noncoding SNPs associated with epilepsy risk alter the expression of PTPRO and GADD45A in brain tissue." (PMID 38212777, 2024). "Expression quantitative trait loci analysis suggested that epilepsy risk single-nucleotide polymorphisms could be responsible for the altered PTPRO and GADD45A expression in human brain tissue." (PMID 38212777, 2024). "Therefore, we hypothesize that these SNPs may contribute to epilepsy risk by regulating PTPRO and GADD45A expression in human brain tissue." (PMID 38212777, 2024). "In this comprehensive analysis of epilepsy, we identified two new potential genes, PTPRO and GADD45A, and highlighted their crucial roles in epilepsy." (PMID 38212777, 2024). "In summary, our findings underscore the potential of PTPRO and GADD45A as promising targets for the diagnosis and treatment of epilepsy." (PMID 38212777, 2024). "To explore the potential role of PTPRO and GADD45A in epilepsy treatment, we first conducted an interaction analysis between the proteins encoded by PTPRO and GADD45A and the targets of approved antiepileptic drugs." (PMID 38212777, 2024). "Second, additional functional characterization would help to better understand the mechanisms of PTPRO and GADD45A in the pathogenesis and treatment of epilepsy." (PMID 38212777, 2024). "The results of this study highlight PTPRO and GADD45A as potential genes for the diagnosis and treatment of epilepsy." (PMID 38212777, 2024). "While our study integrated data from gene expression, gene co-expression, eQTL, PPI network, and drug–gene interaction to uncover the role of PTPRO and GADD45A in epilepsy diagnosis and therapy, there are still some limitations." (PMID 38212777, 2024). "Further analysis revealed that two of these DEGs, PTPRO and GADD45A, had not been previously reported to be associated with epilepsy." (PMID 38212777, 2024).
head and neck cancer (1 paper, 2021). A primary or metastatic malignant neoplasm affecting the head and neck. "Also, downregulation of PTPRO was noted in bladder, colorectal, prostate, breast, lung, ovarian, head and neck cancers of certain data sets." (PMID 35003364, 2021).
hepatitis B virus infection (1 paper, 2020). A viral infection caused by the hepatitis B virus. "We also found that the level of monocyte PTPRO was significantly associated with patient’s age, hepatitis B virus infection, tumor size and tumor number." (PMID 32581055, 2020).
Hyperinsulinemia (1 paper, 2015). An increased concentration of insulin in the blood. "Intriguingly, hyperinsulinemia involving AKT activation was also exacerbated in HFD-fed mice due to PTPRO deletion." (PMID 25826083, 2015). "Hence, PTPRO deletion could contribute to hyperinsulinemia in mice." (PMID 25826083, 2015).
idiopathic nephrotic syndrome (1 paper, 2013). Nephrotic syndrome for which no cause has been identified. "GLEPP-1′s importance in the maintenance of normal glomerular filtration has been shown in patients diagnosed with idiopathic nephrotic syndrome, steroid resistant subtype, that different mutations in PTPRO are to blame in resultant phenotypic changes of podocytes and massive proteinuria." (PMID 24327929, 2013).
myeloma (1 paper, 2017). "Comparison of gene expression profiles (GEPs) of bortezomib-resistant (BR) myeloma cell lines with their drug-naïve counterparts revealed decreased expression of truncated Protein tyrosine phosphatase receptor-type O (PTPROt) in BR cells." (PMID 29371952, 2017).